GINS4 (GINS complex subunit 4)
Diseases named in the same sentence as GINS4 in open-access papers (continued):
Sharing a sentence is not in itself a finding about the gene and the disease.
glioma (6 papers, 2019 to 2024). A benign or malignant brain and spinal cord tumor that arises from glial cells (astrocytes, oligodendrocytes, ependymal cells). "The present study revealed the probable underlying molecular mechanisms of GINS4 in glioma and provided a potential target for improving the prognosis of glioma." (PMID 34556022, 2021). "The result of survival analysis represented that GINS4 expression in gliomas is negatively associated with the survival rate of gliomas." (PMID 34556022, 2021). "Since no previous studies have reported the association between the overexpression of GINS4 and OS in glioma patients, we only included results from seven different data sets in the meta-analysis." (PMID 34556022, 2021). "Therefore, we further speculate that a high level of GINS4 in gliomas may be associated with an unfavorable prognosis of glioma patients." (PMID 34556022, 2021). "Our results suggested that GINS4 was elevated in glioma, and the overexpression of GINS4 was connected with a vast number of clinical features." (PMID 34556022, 2021). "The outcome was suggesting that the level of GINS4 protein increased in glioma tissue compared with the corresponding normal brain tissue." (PMID 34556022, 2021). "The results of CGGA and TCGA databases both indicated that the expression of GINS4 also increased with the age of glioma patients." (PMID 34556022, 2021). "Overall, these results indicate that the expression of GINS4 is correlated with various malignancies of glioma." (PMID 34556022, 2021). "At the same time, we investigated the expression of GINS4 in 17 cases of gliomas and 10 cases of normal brain tissues." (PMID 34556022, 2021). "To reveal the mechanism of GINS4 in gliomas, we used GSEA to evaluate the potential signaling pathway of GINS4 in gliomas." (PMID 34556022, 2021). "The expression level of GINS4 was correlated with the WHO grade of glioma, and as the pathological grade of glioma increase, the average expression level of GINS4 increase." (PMID 34556022, 2021). "Collectively, those analyses and verify results broadened our horizon on the molecular regulation of GINS4 in the complex pathological process of glioma." (PMID 34556022, 2021). "Prior studies had confirmed that some of the GINS4 positive correlation genes play a vital role in the pathology of glioma." (PMID 34556022, 2021). "The next, GINS4 as an independent prognostic factor, which can result in an unfavorable prognosis of glioma." (PMID 34556022, 2021). "Then, we conducted the receiver operating characteristic (ROC) curve based on the CGGA and TCGA data set to explore the diagnosis value of GINS4 in glioma according to the area under the ROC curve (AUC)." (PMID 34556022, 2021). "In conclusion, this study revealed that GINS4, as a promising prognostic biomarker, was upregulated in glioma and positively related to the clinical character and survival of glioma." (PMID 34556022, 2021). "In the first place, the data of GEPIA, GEO and HPA database indicated that GINS4 was upregulated in glioma, and the result of RT-qPCR and IHC staining also proved that the expression of GINS4 was significantly increased both in glioma cell and tissue." (PMID 34556022, 2021). "Collectively, these results revealed that GINS4 is consistently upregulated in both glioma cells and tissue compared with corresponding normal cells and tissue." (PMID 34556022, 2021). "In this study, the biological function of GINS4 in glioma and its relationship with prognosis has been first studied." (PMID 34556022, 2021). "Hence, our finding suggested that GINS4 can be used as a potential prognostic factor that affects the prognosis of patients with glioma." (PMID 34556022, 2021). "However, the mechanism that GINS4 led to an unfavorable prognosis of glioma needs to be further elucidated." (PMID 34556022, 2021). "Moreover, we further explored the influence of the GINS4 expression on the immune microenvironment of glioma patients through the TIMER database." (PMID 34556022, 2021).
glioma (continued). "Moreover, GINS4 potentially promotes the malignant processes of glioma by participating JAK-STAT pathway, etc., other cancer-related pathways, and regulating the immune microenvironment." (PMID 34556022, 2021). "However, no known empirical research has focused on exploring relationships between GINS4 and glioma." (PMID 34556022, 2021). "The univariate and multivariate analyses (an F) results revealed that the upregulation of GINS4 could be used as a prognostic factor for glioma." (PMID 34556022, 2021). "Hence, we can confidently conclude that GINS4, as a prognostic factor, its upregulation can significantly affect the prognosis of patients with glioma." (PMID 34556022, 2021). "Once again, the result of Kaplan–Meier survival analysis, ROC curve, univariate and multivariate analyses, and Meta-analysis was confirmed that GINS4 could be used as an independent prognostic factor to predict poor prognosis in patients with glioma." (PMID 34556022, 2021). "Once more, to use the carcinogenic effect of GINS4 in gliomas for clinical treatment of gliomas." (PMID 34556022, 2021). "On the one hand, this result further illustrates the complexity of the mechanism of GINS4 in glioma, and on the other hand, it also clarifies the potential biological pathway regulation mechanism that GINS4 may participate in the regulation of glioma." (PMID 34556022, 2021). "Next, we further analyzed the relationship between the clinicopathological characteristics of glioma patients and found that the expression of GINS4 was positively correlated with WHO grade, IDH mutation, 1p19 codeletion, PRS_type, and histological subtypes of glioma patients." (PMID 34556022, 2021). "What’s more, univariate and multivariate analyses were performed to explore whether GINS4 is an independent prognostic factor affecting the prognosis of glioma." (PMID 34556022, 2021). "We found some signaling pathways that may be related to the effect of GINS4 on glioma progression, including pathway in cancer, NOTCH signaling pathway, and JAK-STAT pathway." (PMID 34556022, 2021). "Subsequently, GSEA enrichment analysis is used to find the potential molecular mechanism of GINS4 to promote the malignant process of glioma and the anti-glioma drugs that may target GINS4 screened by CMap analysis." (PMID 34556022, 2021). "Although there are many studies have shown that GINS4 plays an important role in tumors, the exact biological function and molecular mechanism of GINS4 in the carcinogenesis of glioma are still unknown." (PMID 34556022, 2021). "Hence, GINS4 act as a novel biomarker plays an important role in the prognosis of glioma and has potential clinical application for improving the prognosis status of glioma." (PMID 34556022, 2021). "Moreover, the expression of GINS4 in recurrent gliomas was higher than that in primary gliomas and was also higher in several histological subtypes." (PMID 34556022, 2021). "GINS4 is an independent prognostic factor that led to a poor prognosis of glioma." (PMID 34556022, 2021). "We performed a meta-analysis to verify the diagnosis role of GINS4 in glioma patients." (PMID 34556022, 2021). "Subsequently, to explore how GINS4 takes part in the malignant progress of glioma." (PMID 34556022, 2021). "In this study, we verified that GINS4 was a prognostic factor in glioma for the first time." (PMID 34556022, 2021). "For all we know, our finding presents the first evidence that GINS4 plays an important role in the carcinogenesis of glioma, providing a potential therapeutic target for the treatment of glioma and providing new hope for improving the survival and prognosis of glioma patients." (PMID 34556022, 2021). "The upregulation of GINS4 predicts an unfavorable prognosis in glioma." (PMID 34556022, 2021). "However, there weren’t studies that have reported the correlation between GINS4 and immune infiltration in gliomas." (PMID 34556022, 2021). "Thus, this study aims to understand and explain the role of GINS4 in glioma." (PMID 34556022, 2021).
glioma (continued). "This suggests that GINS4 may be a potential factor affecting the immune microenvironment of glioma." (PMID 34556022, 2021). "Finally, to further verify the affection of GINS4 on the survival of glioma patients." (PMID 34556022, 2021). "We analyze the relationship between the GINS4 expression level and the WHO grade, age, 1p19_codeletion_status, IDH_mutation_status, PRS_type, and Histology in glioma patients by using the data of CGGA RNA-seq, CGGA microarray data, and TCGA RNA-seq." (PMID 34556022, 2021). "Although there are no reports on the expression and function of GINS4 in gliomas, as a member of the GINS complex, GINS4 plays an important role in cell cycle regulation." (PMID 39458936, 2024). "Then, we further validated that GINS4 RNA levels were upregulated in glioma cells (A172, T98, and U251) compared with correspondence normal cell." (PMID 34556022, 2021). "The results suggested that GINS4 was elevated in gliomas compared with the corresponding normal brain tissues." (PMID 34556022, 2021). "The tumorigenesis of glioma is a complex biological process, and GINS4 is not the only one involved in the malignant process of glioma." (PMID 34556022, 2021). "Nevertheless, a possible role for GINS4 in the oncogenesis of glioma has not been reported to date." (PMID 34556022, 2021).
lung adenocarcinoma (4 papers, 2019 to 2023). A carcinoma that arises from the lung and is characterized by the presence of malignant glandular epithelial cells. "Higher expression of GINS4 poorly linked with overall survival in lung adenocarcinomas." (PMID 31253190, 2019). "GINS4 was reported to contribute to the poor outcome in lung adenocarcinomas." (PMID 33612479, 2021).
sarcoma (3 papers, 2022 to 2024). A usually aggressive malignant neoplasm of the soft tissue or bone. "In the present study, we also found that GINS4 was upregulated in sarcoma tissues and cell lines and was associated with shorter OS and DFS." (PMID 36092720, 2022). "GINS1, GINS2 and GINS4 were positively correlated with the immune cell infiltration in sarcoma microenvironment." (PMID 35896011, 2022). "Our study found high expression of GINS4 in human sarcoma tissues, and it tended to have tight connection with OS and DFS, but failed to achieve significance." (PMID 35896011, 2022). "The GEPIA and Kaplan-Meier Plotter was used to make the investigation of the prognostic ability of GINS1, GINS2, GINS3 and GINS4 expression levels in sarcoma." (PMID 35896011, 2022). "In addition, the mRNA expression levels of the four GINS family members (GINS1, GINS2, GINS3, GINS4) were all higher in sarcoma tissue." (PMID 38473259, 2024). "GINS4 expression was also associated with a relatively poor DFS in sarcoma; however, there was no statistical significance." (PMID 36092720, 2022). "The prognostic relevance tested was also obvious, increased expression of GINS1, GINS2, GINS3 and GINS4 may provide us new therapeutic targets for the treatment of sarcoma." (PMID 35896011, 2022). "By interrogating CCLE, we detected the transcription level of GINS members in many types of cancer cell lines, and got the conclusion that GINS1, GINS2 GINS3 and GINS4 were highly expressed in sarcoma cell lines including Ewing's sarcoma, osteosarcoma and chondrosarcoma." (PMID 35896011, 2022). "The high expression level of GINS1, GINS2 and GINS4 could reduce immune cell infiltration in the sarcoma microenvironment." (PMID 35896011, 2022). "GINS2 and GINS4 expression in sarcoma also affected the OS, although there was no statistical significance." (PMID 36092720, 2022). "The expression level of GINS4 in sarcoma was also higher than in normal samples, but with no significance." (PMID 35896011, 2022).
glioblastoma (2 papers, 2019 to 2021). The most malignant astrocytic tumor (WHO grade IV). "In glioblastoma (GBM), the expression level of GINS4 was positively connected with the Dendritic cell infiltration level (partial cor = 0.185) (p < 0.05)." (PMID 34556022, 2021).
hepatocellular carcinoma (2 papers, 2021 to 2022). A malignant tumor that arises from hepatocytes. "Our research was aimed to identify the expression, clinical value and biological significance of GINS complex subunit 4 (GINS4) in hepatocellular carcinoma (HCC)." (PMID 33842367, 2021).
liver cancer (2 papers, 2018 to 2025). An epithelial or non-epithelial malignant neoplasm that arises from the liver. "Silencing GINS4 can inhibit the proliferation and cell cycle of liver cancer cells." (PMID 40386780, 2025).
fibrosarcoma (1 paper, 2022). A malignant mesenchymal fibroblastic neoplasm affecting the soft tissue and bone. "In Detwiller datasets, highly overexpressed GINS4 was reported in Fibrosarcoma (fold change = 2.441)." (PMID 35896011, 2022).
liver cirrhosis (1 paper, 2021). "Our findings indicate that GINS4 is endowed with a relatively accurate performance to differentiate HCC from liver cirrhosis." (PMID 33842367, 2021). "GINS4 expression was significantly greater in HCC cases with low AFP expression than liver cirrhosis patients from above two datasets." (PMID 33842367, 2021). "As for data from the GSE63898 dataset, GINS4 and AFP expression in HCC were remarkably elevated compared with liver cirrhosis." (PMID 33842367, 2021). "In the GSE25097 dataset, GINS4 and alpha-fetoprotein (AFP) mRNA expression were both prominently greater in HCC than liver cirrhosis tissues." (PMID 33842367, 2021). "ROC curves also demonstrated that GINS4 expression level could effectively distinguish HCC patients from non-tumor individuals (such as healthy controls and patients with liver cirrhosis)." (PMID 33842367, 2021).
neutropenia (1 paper, 2022). A decrease in the number of neutrophils found in the blood. "Here, we describe a familial case of primary immunodeficiency, characterized by a reduced frequency of NK cells, impaired NK cell function, and neutropenia caused by compound heterozygous mutations in GINS4 — namely, a stop codon and a missense variant." (PMID 36345943, 2022). "Immunological phenotypes of the 2 individuals with both GINS4 variants include a substantial reduction of circulating NK cells (with relatively increased frequency of CD56bright NK cells) and neutropenia; however, they have normal B and T cell populations." (PMID 36345943, 2022). "Thus, biallelic partial loss-of-function mutations in GINS4 define a potentially novel disease-causing gene underlying NKD with neutropenia." (PMID 36345943, 2022). "Here, we describe a case of biallelic loss of another CMG helicase component, GINS4, resulting in NKD with neutropenia." (PMID 36345943, 2022).
prostate adenocarcinoma (1 paper, 2022). "GINS4 was correlated with immune cell infiltration in all cancers, especially in BLCA, BRCA, COAD, LIHC, LUAD, prostate adenocarcinoma (PRAD), STAD, thyroid carcinoma (THCA)." (PMID 35365175, 2022).
tumor (24 papers, 2013 to 2026). "In the univariate analysis, viral hepatitis infection, vascular invasion, T classification, M classification, TNM stage, tumor status, residual tumor, and GINS4 expression were significantly associated with the prognosis of HCC (P < 0.05)." (PMID 33842367, 2021). "Similarly, an increase in Hsa_circ_0008673 expression was associated with increased angiogenesis and tumor growth through elevated levels of GINS Complex Subunit 4 (GINS4) and reduced miR-578 absorption." (PMID 41081939, 2025). "As GINS2, GINS4, which were also involved in the DNA replication process, previous studies had reported that they were abnormally expressed in many tumor tissues including KIRC, affecting tumor development." (PMID 37642814, 2024). "To further explore the role of GINS4 in tumor immune, we determined the expression correlation of GINS4 with biomarkers of B cell, CD4 + T cell, neutrophil, dendritic cell and myeloid dendritic cell based on GEO datasets." (PMID 35365175, 2022). "Subtypes with rich stromal components (e.g. GINS2 and GINS4) in human CRC samples were inclined to transform into subtypes with high tumor purity (e.g. GINS1 and GINS3) in corresponding PDX derivatives." (PMID 36345721, 2022). "We also found progressive increase in the GINS4 expression with advanced tumor T classification and TNM stage (P < 0.0001), highlighting that GINS4 expression was positively related to the progression of HCC." (PMID 33842367, 2021). "Multiple databases confirmed the significant upregulation of GINS4 in HCC tissues compared with non-tumor controls." (PMID 33842367, 2021). "The expression of chromatin modifier lymphoid-specific helicase (LSH) and GINS4 was assessed in tumor and normal tissue from 79 patients with NSCLC with clinical characteristics." (PMID 31253190, 2019). "Next, we demonstrated that depletion of GINS4 formed smaller and less abundant tumor spheres that the control cells in H1299 cells through tumor sphere assays (both ** P < 0.01)." (PMID 31253190, 2019). "Functionally, GINS4 overexpression resulted in a ∼1.9-fold increase in cell proliferation, >2-fold increase in migration and invasion, and significantly larger tumor volume in nude mice xenografts (mean tumor volume: 740 mm3 vs. 370 mm3; P < 0.01)." (PMID 41244835, 2025). "GINS4 is essential for cell proliferation in mammals, and its expression is closely related to cell cycle regulation and repair of damaged DNA in normal cells (non-tumor cells), suggesting it is essential for maintaining genomic integrity." (PMID 36092720, 2022). "In terms of negatively correlated GINS4 genes, previous studies have confirmed that they may be a novel tumor suppressor in cancer." (PMID 34556022, 2021). "Greater expression level of GINS4 in above human tumors is positively correlated with malignant biological properties, such as tumor proliferation, colony forming ability, migration, and invasion as well as epithelial-mesenchymal transition both in vitro and in vivo." (PMID 33842367, 2021). "DNA replication is an important step in tumor cell proliferation, so GINS4 might acts a key role in tumor development." (PMID 34556022, 2021). "Moreover, increased GINS4 expression was correlated with worse tumor differentiation, and a significant difference between grade I (well) vs grades II and III (moderate and poor) was found (P=0.003)." (PMID 31754397, 2019). "Thus, suppression of GINS4 potentially represents a novel strategy to retard tumor development." (PMID 33842367, 2021). "Furthermore, GINS4 promoted many characteristics of tumorigenesis including cell growth, clonal formation, migration and invasion, epithelial–mesenchymal transition, tumor sphere and tumor growth in vivo." (PMID 31253190, 2019). "Finally, multivariate analysis showed that the expression level of GINS4 was independent of clinical risk factors such as gender, smoking, tumor differentiation and tumor size, but linked with clinical stages and lymphatic metastasis." (PMID 31253190, 2019).